PTPN12 (protein tyrosine phosphatase non-receptor type 12)
Diseases named in the same sentence as PTPN12 in open-access papers (continued):
Sharing a sentence is not in itself a finding about the gene and the disease.
cancer (continued). "As we were unable to perform a complete cosegregation analysis in this family, or in any of the other PTPN12 or LRP6 families, it remains to be established to what extend carriers of variants in these genes tend to develop cancer at a young age." (PMID 26901136, 2016). "Survival assessment revealed that decreased expression of PTPN12 correlated with adverse cancer-specific survival (Cox regression model, hazard ratio: 0.314, 95% CI: 0.202–0.487, P<0.001)." (PMID 24475046, 2014). "We found that the decreased expression of PTPN12 was a strong and independent predictor of shortened cancer-specific and recurrence-free survival, as evidenced by univariate and multivariate analyses." (PMID 24475046, 2014). "The mechanisms on the potential role of PTPN12 in cancer have been explained in recent investigations." (PMID 24475046, 2014). "Cancers with scores above the obtained cutoff value were considered to have normal PTPN12 expression, which led to the greatest number of cancers classified, based on the presence or absence of a clinical outcome." (PMID 24475046, 2014). "PTPN12 has recently been shown to be downregulated in some cancers, leading to hyperactivity of RTKs (EGFR and MET) and hypersensitivity to TKIs that inhibit these kinases." (PMID 24189400, 2013). "Core pathway analysis revealed that 4 of these 12 target genes - Bmi1, Birc4, Bmpr2 and Ptpn12 - have been found to be significantly deregulated in cancer." (PMID 21846369, 2011). "For instance, the mRNA expression of PTPN12 was up-regulated in ten types of cancer, and connected with drug sensitivity to 9 anti-cancer drugs (e.g., Trametinib, Rs = -0.38, FDR< 3.7 × 10-20) and linked to drug resistance to 33 anti-cancer drugs (e.g., THZ-2-102-1, Rs = 0.32, FDR< 7.1 × 10-23)." (PMID 36341348, 2022). "PTPN12 immunostaining was more prevalent in ERG fusion positive than in ERG wild type cancers." (PMID 31606028, 2019). "Collectively, these data suggest that PTPN12 functions as a suppressor of malignant transformation and may be inactivated in human cancers." (PMID 25663493, 2015). "However, previous studies essentially pointed to PTPN12 as a key regulator of cellular motility and cytoskeleton dynamics involved in immunity, cancer, and development." (PMID 26594644, 2015). "Collectively, these data suggest that PTPN12 functions as a suppressor of malignant transformation and may be inactivated in cancers." (PMID 24475046, 2014). "Besides, miR-200b has also been associated with cancer chemo-sensitivity by modulating PTEN, PTPN12 and thus their downstream oncogenes like src and ras." (PMID 24447584, 2014). "Therefore, we hypothesized that the temporal dynamics of EMT regulatory genes (e.g., ACSS1 or PTPN12) could be exploited to predict cancer progression." (PMID 33667222, 2021). "Furthermore, in cancers with loss of a common negative feedback inhibitor of RTK activation such as loss of PTPN12 expression, single-agent RTK inhibition is ineffective because of hyperactivation of multiple RTKs." (PMID 33411917, 2021). "Moreover, PTPN12 retained prognostic impact in molecularly defined high risk groups such as in PTEN deleted cancers and in some morphologically defined high-risk groups such as in Gleason 3 + 4 cancers." (PMID 31606028, 2019). "The CNV percentage in pan-cancer indicated that heterozygous amplification in cancers were widely found in genes PTPN1, PTPN7, PTPN12 and PTPN14 in most cancers, while heterozygous deletions were widely found in genes PTPN13, PTPN20, PTPN22 and PTPN23." (PMID 37884566, 2023). "One was the DEGs between a cancer cell line and the corresponding gene DKO (E3 ubiquitin‐protein ligase (CBL)‐PTPN12 DKO case)." (PMID 34723439, 2021). "PTPN12 staining was seen in 86.4% of TMPRSS2:ERG fusion positive but in only 58.4% of ERG negative cancers." (PMID 31606028, 2019).
cancer (continued). "The striking prognostic role of high PTPN12 expression being independent of all established prognostic features available before and after prostatectomy in our study on 13,660 cancers was not expected." (PMID 31606028, 2019). "Multivariate analyses revealed an independent prognostic impact of high PTPN12 expression in all cancers and in the ERG negative subgroup and to a lesser extent also in ERG positive cancers." (PMID 31606028, 2019). "The average Ki67LI increased from 1.82 in PTPN12 negative cancers to 3.61 in cancers with strong PTPN12 staining." (PMID 31606028, 2019). "Our data identify PTPN12 protein as another protein whose expression was increased in ERG positive compared to ERG negative cancers." (PMID 31606028, 2019). "PTPN12 staining was typically absent or weak in normal prostatic epithelium but seen in the majority of cancers, where staining was considered weak in 26.5%, moderate in 39.9%, and strong in 4.7%." (PMID 31606028, 2019). "Tyrosine-protein phosphatase nonreceptor type 12 (PTPN12) has been proposed to predict prognosis of various human cancers." (PMID 25663493, 2015). "The hazard ratio for PSA recurrence after radical prostatectomy for strong versus negative PTPN12 expression was in the univariate model a weak 1.85 for all cancers and a moderate 2.50 in the ERG negative subset as compared with 6.01 for the Gleason grade at biopsy." (PMID 31606028, 2019). "These analyses identified PTPN12 as an independent prognostic feature in all 4 scenarios, if the entire cohort or the subgroup of ERG negative cancers was considered (p < 0.0005 each)." (PMID 31606028, 2019). "Negative PTPN12 staining was seen in 32% of HER2 negative cancers and in 17% of HER2 positive cancers." (PMID 31606028, 2019). "PTPN12 immunostaining was seen in 86.4% of ERG IHC positive and in only 58.4% of ERG IHC negative cancers (p < 0.0001)." (PMID 31606028, 2019).
PTPN12 also shares sentences with these, for which no sentence is quoted: stomach adenocarcinoma (2 papers); astrocytomas (1); bladder transitional cell carcinoma (1); diabetes (1); diffuse large B-cell lymphoma (1); gastric cancer (1); hereditary cancer (1); Huntington disease (1); laryngeal squamous cell carcinoma (1); leukemia (1); lymphoid neoplasm (1); metabolic disease (1); muscular dystrophy (1); oral squamous cell carcinoma (1); pancreatic adenocarcinoma (1); rectum adenocarcinoma (1); renal cell carcinoma (1); retinitis pigmentosa (1); sarcoma (1); skin cutaneous melanoma (1); stomach cancer (1); thymoma (1); type 2 diabetes (1); uveal melanoma (1); Vascular tumors (1).